IL6 (interleukin 6)
Diseases named in the same sentence as IL6 in open-access papers (continued):
Sharing a sentence is not in itself a finding about the gene and the disease.
tumor (continued). "In some rodent models, tumor and non-tumor cells in the TME (e.g., leukocytes, fibroblasts, endothelial cells) secrete inflammatory mediators such as interleukin (IL)-1, tumor necrosis factor (TNF)-α, IL-6, IL-8, IFN-α, IL-10, IL-12, TGF-β, and CXCR4." (PMID 34200240, 2021). "While B-ALL cells do not produce IL-6 themselves, they cause an upregulation in IL-6 production by the tumor microenvironment, regardless of comparable tumor burdens in both WT & IL-6 KO mice." (PMID 34711820, 2021). "Interestingly, MSA treatment didn’t reduced the tumor number of 4NQO-induced IL-6 KO mice, MSA-mediated tumor suppression was abolished." (PMID 34393797, 2021). "We further found that TNF-α treatment increased not only the phosphorylation of p65 but also the expression of Il-6 in a dose- and time-dependent manner and that treatment with the NF-κB inhibitor BAY-11-7082 reversed the expression of Il-6 in tumour cells." (PMID 33654093, 2021). "Moreover, IL-1β induces lipolysis of adjacent adipocytes and the expression of metastasis-related and inflammatory factors such as matrix metalloproteinases (MMP), COX-2, CCL2, IL-6, TGF-β, and IL-8 which promote tumor growth and bone metastasis." (PMID 34064859, 2021). "In addition, IL-6 released by TAMs, in turn, would further activate the STAT3 pathway, forming a positive feedback loop between tumor and TME cells." (PMID 34638305, 2021). "These include SCF, IL-6 and others, the profile of which are highly tumor-type dependent and not the focus of this discussion." (PMID 33922465, 2021). "Indeed, the expression of IL-6 or IL-8 in ESCC tumor tissues was found to impair NK cell function and positively correlated with tumor progression and poor survival." (PMID 33390169, 2021). "IL-6 activated STAT3 and NF-kB/TIM4 signals to regulate tumor progression." (PMID 34657635, 2021). "In addition, interleukin-6 (IL-6), interleukin-11 (IL-11), and tumor necrosis factor alpha (TNF-α) produced in tumor cells also enhance osteoclast formation and activation or osteoclast precursor activation." (PMID 33672879, 2021). "In LLC xenograft mice, endostatin inhibited tumor angiogenesis by reducing the number of CD31+ cells and VEGF expression, aggravated hypoxia, and increased levels of inflammatory cytokines (IL-4, IL-6, IL-10) in tumor and CCL2 expression in endothelial cells and fibroblasts." (PMID 34209679, 2021). "As such, anti-IL-6 monotherapy fails to induce a robust anti-tumor activity and to overcome GBM resistance to checkpoint blockade, likely due to reduced co-stimulatory CD40 signal and insufficient T-cell infiltration and activation." (PMID 34103524, 2021). "IL-6 mRNA was detected at the tumor site of cachexigenic clone (c20)- but not at that of noncachexigenic clone (c5)-bearing mice." (PMID 33557173, 2021). "The absence of RIPK3 exhibits dramatically increased tumor numbers in Apcmin/+ mice through the hyperactivation of IL-6/STAT3 signals." (PMID 33996591, 2021). "Furthermore, it was found that the LLC tumor group showed high levels of TNF-α, IL-1β, and IL-6, and Alp reduced their serum concentrations in a dose-dependent manner." (PMID 34093209, 2021). "It has been reported that IL-10 produced by MDSCs could decrease the secretion of IL-6, IL-12, and tumor necrosis factor-α (TNF-α) of macrophages, which remarkably suppress their anti-tumor activity." (PMID 35004667, 2021). "Additionally, BM-MSCs also contributed to tumor angiogenesis by secreting pro-angiogenic factors, such as VEGF and IL-6, as well as to differentiating into pericyte-like cells." (PMID 33744858, 2021). "In support of this hypothesis, we found large necrotic areas within the tumor and high amount of the inflammatory cytokines MCP-1 and IL6 and of immunosuppressive cytokine IL10." (PMID 34604232, 2021).
tumor (continued). "Binding of IL-6 to its receptor IL-6R in cancer cells activates multiple cellular signalling pathways including JAK/STAT, PI3K/Akt, leading to enhanced expression of a variety of promoters of tumour growth, angiogenesis and cancer progression." (PMID 34223877, 2021). "Surprisingly, we found that doxorubicin-treated mice lacking IL-6 in the tumor microenvironment live significantly longer than WT-treated mice, with a majority of mice appearing to be cured of their disease." (PMID 34711820, 2021). "The IL-6 mediated STAT3 activation upregulates many downstream target genes involved in proliferation, invasion, migration, and EMT of HNSCC, suggesting its role in aggressive tumor behavior." (PMID 33925575, 2021). "In addition, ARID1A and PIK3CA mutations were found to cooperate to promote tumor growth through sustained IL-6 overproduction, and IL-6 was identified as a physiological target of ARID1A tumor suppressor activity." (PMID 33758607, 2021). "Next, we aimed to investigate whether suppression of p16 leads to decreased expression of IL6 and CXCL8 in tumor cells." (PMID 33550279, 2021). "Of note, many cytokines which activate the tumour microenvironment, including platelet-derived growth factor, B polypeptide (PDGFB), interleukin-6 (IL6), chemokine (C–C motif) ligand 2 (CCL2), and leukaemia inhibitory factor (LIF) were included as targets of TGF-β." (PMID 33674758, 2021). "Expression of ZEB1 in tumor cells leads to induction of EMT and stemness, and functions at both sides of the tumor-stroma interface by regulating the production of connective tissue growth factor (CTGF), hepatocyte growth factor (HGF), and interleukin 6 (IL6), to boost tumor progression." (PMID 35111082, 2021). "Similarly, IL-6/STAT3 signaling has been described in other tumors such as osteosarcoma, and targeting this axis has been proposed for ablating tumor-stroma crosstalk." (PMID 33287630, 2021). "Activation of pyroptosis by CAR-T cells when they face tumor cells leads to the release of factors that activate caspase 1 for GSDMD cleavage in macrophages, which results in massive amounts of cytokines, including IL6 and IL1β." (PMID 34685542, 2021). "The secretion profile of some of the cytokines related to inflammation in addition to tumor invasion, progression, and migration, namely, IFN-γ, TNF-α, IL-1β, IL-6, IL-8, and IL-12, demonstrated a decrease in values following treatment with the hWJSC-CC, hWJSC-CM (100%), and hWJSC-L (15 μg/ml)." (PMID 33869169, 2021). "Moreover, IL-6 upregulates the expression of the androgen receptor and of CXCR4 on tumor cells, thereby favoring tumor cell proliferation and recruitment to bone via the CXCL12/CXCR4 axis." (PMID 34064859, 2021). "TGFB1, IL1B, IL10, IL6, PTGS2, and PPARG closely interacted with the tumor microenvironment." (PMID 34394377, 2021). "We found that whole-tumor gene expression of T cell marker factors (CD8 and IFN-γ) and chemokines (CXCL9 and CXCL10) were significantly enhanced after ICT treatment, while inflammatory factors (IL6, IL10 and TNF-α) were reduced." (PMID 33460401, 2021). "Upstream regulator prediction revealed IL-6 identified as the top upstream regulator in the fat of KPC tumor mice; neither IL-6 nor STAT3 was discovered among upstream regulators in adipose of mice with KPC IL6KO tumors." (PMID 33851955, 2021). "Additionally, LLC tumor-induced increase of circulating TNF-α and IL-6 was abolished in TLR4 KO mice." (PMID 34093869, 2021). "IL6 is the main inducer of the STAT3 pathway in NSCLC and promotes tumour growth." (PMID 33122847, 2021). "Besides, supplementation with a combination of fish oil and selenium increase soleus and gastrocnemius muscle mass and reduces IL-6, TNF-α, and myostatin levels in gastrocnemius of tumor-bearing C57BL/6 mice." (PMID 34199575, 2021).
tumor (continued). "In cancer cachexia, both tumor cells and tumor-activating immune cells express proinflammatory cytokines, including tumor necrosis factor (TNF)-α, interleukin (IL)-1, IL-6, IL-8, and interferon (IFN)γ, all of which systemically affect various organs such as the brain, liver, muscle, and fat." (PMID 33801569, 2021). "On the other hand, KCs can induce cell adhesion molecule expression on LSECs, which helps the adhesion of disseminated tumor cell arrest in liver, and produces factors (e.g., IL-6, MMPs, VEGF, etc.)that promote tumor cell invasion, proliferation, and angiogenesis." (PMID 34067719, 2021). "Of note, inflammatory cytokines such as TNFα, IL-6, and IL-8 and platelet agonists such as thrombin and ADP in the tumor microenvironment could promote platelet autophagy and then activate platelets, leading to thrombosis and cancer metastasis." (PMID 34722319, 2021). "Visceral, but not subcutaneous, adipocytes promote tumor proliferation and induce epithelial-to-mesenchymal transition via IL-6 and IL-8." (PMID 34439387, 2021). "We also analyzed the impact of gemcitabine treatment on the expression of several tumor-promoting genes-TPGs (IL8, IL6, CD44 and CD133) as well as CD95L in experimental tumors derived from the PancTuI-luc cell line with two different settings of treatment (palliative and adjuvant)." (PMID 34771621, 2021). "Aside from recruiting TAMs, transformed CAFs may secrete cytokines such as IL-6, IL-8, IL-17, TNF-α, and VEGF that does not only contribute towards tumor aggressiveness but also in therapy response such as in 5-FU treatment." (PMID 34571731, 2021). "Hybridization signals (brown dots) for IL-10 or IL-6 were found in the cytoplasm of CD30-positive cells in both the BI-ALCL seroma and in the BI-ALCL xenograft, which consisted of pleomorphic tumor cells with highly atypical nuclei and prominent nucleoli encircling central necrotic areas." (PMID 33146828, 2021). "IL-6 binds with IL-6R to induce the activation of STAT3, and activated STAT3 binds to the promoter region of the VEGF gene to increase transcription, promoting the formation of tumor angiogenesis." (PMID 34976809, 2021). "Chronic inflammation is the key driver of the CAC; the RNA-seq transcriptome study demonstrated that MSCs reduce tumor initiation through immune responses, so we detected pro-inflammatory cytokines TNF-α, IL-1β, and IL-6 in serum to determine the systematic immune responses." (PMID 34150751, 2021). "Furthermore, IL-6 also influences the vasculature by regulating VEGF and disrupting pericytes coverage of blood vessels in the tumor microenvironment." (PMID 34754042, 2021). "IL-6 favors PD-L1 upregulation, and reciprocally increases CCL2 tissue levels, resulting in an amplification loop that promotes monocyte infiltration, malignant cell proliferation and tumor survival." (PMID 34830209, 2021). "Although dose‐related increase of several proinflammatory cytokines (such as IL‐1β, TNF‐α, IL‐6, and IL‐12) was observed, no patients experienced objective tumor regression." (PMID 33854892, 2021). "Tumor-derived factors, such as G-CSF (also known as CSF3), GM-CSF (also known as CSF2), and IL-6 drive this myeloid bias and increase the circulating and tumor-infiltrating MDSC population, which accelerates tumor progression by suppressing T cell responses and releasing metabolic factors." (PMID 34248988, 2021). "Besides, we explored the correlation of alternative polyadenylation of these genes and ccRCC prognosis as well as the IL6-JAK-STAT3 pathway and tumor microenvironment." (PMID 34660570, 2021). "MSC cytokine loops including IL-6 and CXCL-7 regulate CSCs and accelerate tumor growth." (PMID 33806802, 2021). "Moreover, a positive IL-6/STAT3/RTVP-1 feedback loop was shown to be responsible of increased mesenchymal transformation, invasiveness and resistance to anti-tumour treatments in glioma cells." (PMID 34361105, 2021).
tumor (continued). "CAAs secrete more chemokine (C–C motif) ligand 2 (CCL2), CCL5, interleukin-1β (IL-1β), IL-6, TNF-α, vascular endothelial growth factor (VEGF) and leptin, etc., which could facilitate the invasion of the tumor and immune escape." (PMID 33413697, 2021). "In fact, it was not until recent decades that the function of IL-6 in restraining tumor growth with hyperthermia came to be noticed." (PMID 33390844, 2021). "Furthermore, hMSC treatment promoted HCC progression, increased IL-6 and TNF-α expression, and decreased the number of natural killer (NK) cells in tumor niches." (PMID 33849537, 2021). "Bmi-1 is uniquely expressed in head and neck CSC (as opposed to bulk tumor cells), and we showed that this effect is enhanced by IL-6 signaling." (PMID 34689150, 2021). "Loss of quadriceps mass and circulating levels of murine IL-6 (mIL-6) correlated negatively with survival, although tumor mass did not." (PMID 33851955, 2021). "Our in vitro study showed that hypoxic stress did not induce IL1A or IL6 expression in tumor cells or macrophages but dramatically enhanced their expression when co-cultured with tumor cells." (PMID 34362882, 2021). "In the tumor microenvironment, potential stimuli that activate fibroblasts include bone morphogenetic protein (BMP), interleukin-1, interleukin-6, platelet-derived growth factor (PDGF), sonic hedgehog (SHH), reactive oxygen species (ROS), transforming growth factor-β (TGF-β), as well as TNF." (PMID 33614646, 2021). "But, other transcriptional targets and the putative systemic effects of IL6 have not been further explored in this tumor type." (PMID 34422669, 2021). "TAMs initiate a tumor-promoting microenvironment and may cause tumor evasion from immune destruction by elaborating various cytokines (e.g., IL1, IL6, TNF-α) and growth factors (e.g., TGF-β) that reduce T-cell activity and T cell-mediated tumor elimination." (PMID 34577857, 2021). "Nonetheless, the expression of inhibitory and suppressive markers, including genes for IL-4R, IL-10, IL-6, VEGFA, CCL2 and IL-1β, were mostly expressed by cluster 0, suggesting that these cells had a tumor-promoting and immune-suppressing functions, which resemble MDSC-like cells." (PMID 34025646, 2021). "In addition, a variety of tumor-originated cytokines, such as G-CSF, VEGF, IL-6, and IL-1β, have been proven to promote MDSCs accumulation." (PMID 34899747, 2021). "Furthermore, scientific data show the upregulation of serum IL-6 in CRC, which correlates with the tumor size but, also, with poor prognosis in metastatic colon cancer patients and treatment-refractory carcinomas." (PMID 33923292, 2021). "Consistent with these actions, 1,25(OH)2D treatment in mice with 4-NQO-induced squamous cell carcinoma decreased invasive cancer, reduced tumor MDSC number, blocked IL-6 induced recruitment of MDSC, and reduced the T-cell suppressive capacity of MDSC from the tumor." (PMID 34066482, 2021). "It is possible that Th17 is promoted in the presence of increased TGFB1 with non-diminished IL6 or that Th17 infiltrates to the tumor, upon which the tumor microenvironment promotes memory differentiation." (PMID 34307352, 2021). "Thus, there were significant differences in the production of cytokines IFN-γ, IL-6, and TNF-α between naïve and transfected MSCs on the one hand, and naïve and transfected tumor Huh7.5 cells on the other hand." (PMID 34360889, 2021). "EGFR-induced mTOR can stimulate the expression of IL6 through the classic pathway and reprogram IL-6 nonresponsive cells into IL-6 responder cells, to further affect the sensitivity of the tumor cells to IL-6." (PMID 33582655, 2021). "Our reported increases in IL-6 and IL-10 post-IGA are similar to previous reports in several tumour types and similarly the most marked changes were seen following CRYO in this earlier study although this was based on only 4 patients treated with CRYO compared with 31 treated with RFA or MWA." (PMID 34885149, 2021).
tumor (continued). "Therefore, α-IL-6 and α-CTLA-4 combination treatment led to effective and long-lasting anti-tumor activity." (PMID 34093869, 2021). "Therefore, targeting IL-6 is a reasonable strategy for MDSC management, and attempts in combination application with ICIs in tumor treatment are warranted." (PMID 34689842, 2021). "Although the absence of IL-6 improved anti-tumor immune function, this response is potentially hampered by enhanced PD-L1 expression on tumor cells." (PMID 34504657, 2021). "Thus, several studies have shown that IL-6, and downstream STAT3 signaling, is a critical tumor-promoting cytokine in CAC." (PMID 34884543, 2021). "In summary (graphical abstract), we reveal that SPTBN1 functions as a tumor suppressor to stabilize SOCS1 protein, controlling the cellular level of p65 to suppress the expression of inflammatory cytokines, IL-1α, IL-1β and IL-6, and the expansion of MDSCs and Foxp3+Treg cells." (PMID 33754058, 2021). "Moreover, IL-1 beta-induced expression of TNF-alpha, IL-6, IL-8, IL-17, COX-2, and PGE2, pro-inflammatory mediators, and pro-tumor factors supporting tumor growth cells." (PMID 35008550, 2021). "Also, WCE rich in flavonoids suppressed IL-6, CXCL1, and CXCL8 thus reducing tumor-elicited infiltration MDSCs, TAMs, and endothelial cells accompanied by reduced STAT3 activation, in MDSCs in PC-3 and DU145 prostate cancer xenografts." (PMID 34950252, 2021). "Thus, in addition to its influence on promoting tumour cell spreading by interaction with tumour cell-associated MUC1 as reported in our earlier study, circulating PNA could also influence metastasis by enhancing the secretion of metastasis-promoting MCP-1 and IL-6 from the endothelium." (PMID 34223877, 2021). "IL-6 signaling induces and activates STAT3, supporting cancer cell survival and proliferation by upregulating expression of the anti-apoptotic protein, Bcl-2, in various tumor cell lines, such as melanoma cells." (PMID 33917793, 2021). "CAF with tumor-promoting functions secrete growth factors (HGF, IGF1, CTGF, PDGF, VEGF, LIF), cytokines (IL-1, IL-4, IL-6, IL-8, IL-10, TGF-β), and chemokines (CCL2, CCL5, CXCL5, CXCL9, CXCL10, CXCL12), WNT5α, and bone morphogenic protein 4 (BMP4), which promote tumor progression." (PMID 35008832, 2021). "Cox regression analysis further showed that high IL6 expression is a predictor of poorer prognosis independent of tumor stage (HR = 4.57, 95% CI= 1.54-13.55, p = 0.006)." (PMID 34422669, 2021). "The BO-treatment significantly inhibited the mRNA expression of IL-6 and TNF-α in tumor tissues." (PMID 34869511, 2021). "We also previously showed that the loss of TIMP3 in cells and in tumors generated in NOD-SCID mice lacking RNase activity led to increased IL-6 expression and was correlated with tumor progression." (PMID 34657130, 2021). "Based on the tumor-promoting characteristic of PI3K/AKT pathway and previous studies on AKT-regulating IL-6 expression, we subsequently assessed the effects of PI3K/AKT activators on IL-6 levels." (PMID 35111682, 2021). "In OSCC, NF-κB is constitutively activated and is associated with the upregulation of different inflammatory genes, including IL-6, IL-8, CCL5, and CXCL10, and is considered a major factor responsible for the inflammatory infiltrate observed in the tumor microenvironment (TME)." (PMID 35047997, 2021). "Furthermore, the induction of IL-6 is found to increase the expression of ALDH1, a CSC marker, and TWIST, an essential EMT inducer, in a xenograft tumor model." (PMID 33390169, 2021). "The research on the molecular mechanisms of IL-6 activity indicates a negative role of this cytokine in the process of carcinogenesis, tumor development and metastasis." (PMID 34572929, 2021).